TGFBR2 (transforming growth factor beta receptor 2)
Diseases named in the same sentence as TGFBR2 in open-access papers (continued):
Sharing a sentence is not in itself a finding about the gene and the disease.
melanoma (21 papers, 2012 to 2025). A malignant, usually aggressive tumor composed of atypical, neoplastic melanocytes. "TGFβ signaling through TGFBR2 expression enhances melanoma invasion and motility, and TGFβ ligands induce their own expression through a positive amplification loop." (PMID 35179962, 2022). "It has been well documented that miR-211 is a lineage-specific miRNA which is highly expressed in the melanocytic lineage and has been associated with melanoma cell invasiveness via its direct regulation of POU3F2 (BRN2), IGF2R, TGFBR2, NFAT5, and NUAK1." (PMID 25980496, 2015). "Supporting this observation, we also found that CS score was positively correlated with PD-L1 in melanoma and with TGF-beta receptor TGFBR2 in metastatic urothelial cancer." (PMID 35368664, 2022). "Combined in vitro and in vivo screening revealed the most promising CSR, such as TGFBR2-4-1BB, which enhanced the anti-tumor function of NY-ESO-1 TCR+ T cells in a human melanoma xenograft mouse model." (PMID 32570906, 2020). "Some of the researchers implied it as a tumor suppressor by targeting oncogenic genes such as IGF2R, TGFBR2 and NFAT5 in melanoma." (PMID 28924391, 2017). "Expression levels of miR-211 are inversely related to melanoma cell migration and invasion, and it has been shown to function as a tumour-suppressor through target genes including IGF2R, TGFBR2 and NFAT5." (PMID 27852308, 2016). "Ectopic expression of these miRNAs in melanoma cells differentially alters the expression of five exemplar TargetScan-predicted target genes: ADAR1, ITGB8, TGFBR2, MMP2 and VEGF-A." (PMID 24920276, 2014). "Here we show that SALL4 can build a protein complex together with HDAC2 also in human melanoma cells and that SALL4 and HDAC2 together directly bind to genes involved in melanocyte and melanoma biology, such as VEGFR-1, CDH2 (N-cadherin), FN1, TGFBR2, MITF, and others." (PMID 34417458, 2021). "Moreover, we constructed a miRNA–miRNA interaction network using the miRNet tool, revealing key regulatory genes in melanoma, including PLAG1, TGFBR2, CDKN2A, MAPK14 and MYC, which exhibited significant degrees and betweenness centrality in the network analysis." (PMID 39823244, 2025). "MiR-211 is encoded within the sixth intron of TRPM1, a candidate suppressor of melanoma metastasis, and previous researches demonstrated that overexpression of miR-211 inhibited both anchorage-independent colony formation and invasion, through regulation of IGF2R, TGFBR2, NFAT5 and BRN2." (PMID 23155457, 2012).
glioblastoma (19 papers, 2016 to 2025). The most malignant astrocytic tumor (WHO grade IV). "Another study in glioblastoma-bearing mice treated with allogeneic NK cells showed that TGFBR2 knockout prevented NK-cell dysfunction and tumor growth." (PMID 39376560, 2024). "For example, LncRNA MIR4435-2HG potentiates the proliferation and invasion of glioblastoma cells via modulating miR-1224–5p/TGFBR2 axis." (PMID 33505307, 2020). "MET and TGFBR2 gene expressions were found to positively correlate in several other tumor entities, such as prostate adenocarcinoma, thymoma, glioblastoma, head and neck squamous cell carcinoma, testicular germ cell tumors, and esophageal carcinoma." (PMID 30004628, 2018). "Treatment of glioblastoma stem cell-engrafted mice with allogeneic NK cells in combination with inhibitors of integrin or transforming growth factor (TGF)-β signaling or with TGFBR2 gene-edited allogeneic NK cells prevented NK cell dysfunction and tumor growth." (PMID 37475035, 2023). "A phase I clinical trial with a window-of-opportunity component of engineered NK cells containing deleted TGFBR2 and NR3C1 in recurrent glioblastoma is planned (NCT04991870)." (PMID 37475035, 2023). "In the treatment of glioblastoma multiforme (GBM), disruption of the TGFBR2 gene in NK cells could restore the antitumor activity of NK cells." (PMID 36428748, 2022). "Moreover, silencing of TGFBR2 can abolish TGFB-induced invasion and migratory responses of glioblastoma in vitro." (PMID 27716259, 2016).
glioma (18 papers, 2011 to 2025). A benign or malignant brain and spinal cord tumor that arises from glial cells (astrocytes, oligodendrocytes, ependymal cells). "Propofol inhibited glioma cell proliferation, migration, and invasion by regulating the miR-410-3p/transforming growth factor-B receptor type 2 (TGFBR2) axis, the miR-206/Rho-associated protein kinase 1 (ROCK1) axis, and miR-134 expression, as well as suppressing the PI3K/Akt signaling pathway." (PMID 38786726, 2024). "Treatment of glioma stem cell-engrafted mice with allogeneic NK cells in combination with inhibitors of integrin or TGF-β signaling or with TGFBR2 gene-edited allogeneic NK cells prevented glioma-induced NK cell dysfunction and tumor growth." (PMID 36792722, 2023). "Specifically, MIR4435-2HG propels the advancement of glioma by targeting the miR-1224-5p/TGF-β receptor type 2 (TGFBR2) axis." (PMID 37998733, 2023). "Another recent study reported that EMP3 directly interacts with TGFBR2 in glioma cells, which subsequently activates the TGF‐β/Smad2/3 pathway and enhances tumor progression in vitro and in vivo." (PMID 34268874, 2021). "In our study, we observed that TGFBR2 expression was higher in the glioma cell line than TGFBR1 and TGFBR3." (PMID 33576874, 2021). "It has been reported that knockdown of TGFBR2 markedly inhibits the invasiveness of glioma stem-like cells." (PMID 33576874, 2021). "Propofol exhibits antitumoral properties in glioma cells at least in part by modulation of the miR-410-3p/TGFBR2 pathway." (PMID 33205044, 2020). "Moreover, MIR4435-2HG functions as a sponge to absorb miR-1224-5p, inhibiting its expression and consequently enhancing the expression of transforming growth factor beta receptor 2 (TGFBR2), thus driving the advancement of glioma." (PMID 37998733, 2023). "Furthermore, research conducted by Ye XZ and colleagues has indicated that knockdown of TGFBR2 (Transforming Growth Factor Beta Receptor 2) diminishes the invasive potential of glioma cells." (PMID 37700840, 2023). "It has been reported that EMP3 directly interacts with TGFBR2 in glioma cells." (PMID 37887529, 2023). "Emerging evidence suggests TGFBR2 signaling can support oncogenic mechanisms in glioma cells, including resistance to therapy and maintenance of the stem cell phenotype, and blocking these signaling in gliomas may offer therapeutic advantages in the context of recurrent disease." (PMID 40301302, 2025). "After silencing PSMB8, reduced expression of TGFBR1 and TGFBR2 led to decreased phosphorylation of SMAD2/3, which inhibited the malignant behavior of glioma cells." (PMID 40335825, 2025). "The oncogenic effect of miRNA-21 in human glioma cells is implemented through the suppression of such tumor suppressor genes as TAp63, HNRPK, JMY, TOPORS, RECK, TP53BP2, TIMP3, PDCD4, and TGFBR2/3." (PMID 37033545, 2023). "Knockdown of TGFBR2 expression in glioma cells significantly reduced the promotion of GSC by Tregs, confirming that TGF-β-TGFBR2 mediated the role of Treg-induced GSCs properties." (PMID 33576874, 2021). "Additionally, CEBPB and TCF12 might function in glioma through targeting others (CEBPB → TCF12, CEBPB → TGFBR2, and TCF12 → TGFBR2)." (PMID 27716259, 2016). "CEBPB might act in glioma by regulating CCL2, CCND1, THBS1, THBS2, SMAD5, SMAD6, TGFBR2, and TCF12." (PMID 27716259, 2016).
aneurysm (16 papers, 2014 to 2025). Bulging or ballooning in an area of an artery secondary to arterial wall weakening. "TGF-β1 neutralizing antibodies or TGFBR2 mutations can increase the instability of aneurysms." (PMID 36972239, 2023). "Furthermore, higher plasma levels of TGF-beta 1 could also be an effect of altered binding ability to its receptors, TGFBR1 and TGFBR2, caused by the occurrence of genetic variants in these receptors that were previously associated with aneurysm development." (PMID 37569462, 2023). "More recently, a mutation in the TGFBR2 gene was reported in a patient classified as aortic dilatation/aneurysm but otherwise not well defined clinically." (PMID 24564502, 2014).
aortic aneurysm (16 papers, 2013 to 2023). A ruptured aneurysm located in the wall of the proximal portion of the descending aorta proceeding from the arch of the aorta. "In accordance with this, pathological roles have been ascribed to variants of the transforming growth factor beta receptor 2 (TGFBR2) in aortic aneurysm, Kawasaki disease and sudden cardiac arrest against the background of coronary artery disease." (PMID 26146998, 2015). "In conclusion, loss of SMC-Tgfbr1 triggers multiple deleterious pathways, including abnormal TGFBR2, ERK, and AngII/AT1R signals that disrupt aortic wall homeostasis to cause aortic aneurysm formation." (PMID 27739498, 2016). "Results from our study show that SMC-Tgfbr1 deletion promoted aortic aneurysm formation in a manner partially dependent on Tgfbr2 in adult mice." (PMID 27739498, 2016). "Additionally, mutation of TGF-β signal pathway components such as TGFBR1 and TGFBR2 is directly involved in the progression of the aortic aneurysm." (PMID 33788038, 2021). "Regarding to TGFBR1 and TGFBR2 genes, in contrast with a recent paper showing a missense mutation in TGFBR2 gene in a patient with BAV and aortic aneurysm, our findings support the studies suggesting that mutations in these genes are rarely identified in patients with familial BAV." (PMID 23578328, 2013). "Recently, a missense mutation in transforming growth factor-beta receptor 2 gene (TGFBR2) was found in a patient with BAV and aortic aneurysm, but earlier studies found no mutation in either TGFBR1 or TGFBR2 in patients with familial and sporadic BAV disease." (PMID 23578328, 2013). "However, up to now, no large genomic rearrangements in TGFBR1 or TGFBR2 have been reported in patients with aortic aneurysm/dissection and LDS features." (PMID 30286810, 2018). "On the other hand, in postnatal SMC-specific Tgfbr2 knockout mice and LDS, the intact TGF-β receptor complexes are theoretically below one-fourth of the wild-type, which might be insufficient for the aortic wall maintenance and prevention of aortic aneurysm formation." (PMID 30037098, 2018). "A total of 115 patients with suspected MFS or early-onset aortic aneurysm/dissection, who had a negative result in a 15-gene panel testing, were included in this study and evaluated for gross deletions and duplications in FBN1 and TGFBR2 gene by MLPA assay." (PMID 30286810, 2018).
pulmonary fibrosis (14 papers, 2016 to 2025). Chronic progressive interstitial lung disorder characterized by the replacement of the lung tissue by connective tissue, leading to progressive dyspnea, respiratory failure, or right heart failure. "NEDD4L alleviates experimental pulmonary fibrosis by targeting ubiquitination of TGFBR2 in lung fibroblasts." (PMID 38267743, 2024). "Viral induction of TGFB1 predicts profibrotic signaling to most epithelial cells and fibroblasts expressing both TGFBR1 and TGFBR2, including myofibroblasts, which constitute the fibroblast foci in lung fibrosis." (PMID 38597954, 2024). "In the present study, MHP1-AcN decreased TβRI and TβRII expression in fibroblasts, but in bleomycin-induced lung fibrosis model, MHP1-AcN treatment inhibited the increase in Tgfbr2 without significant change in Tgfbr1 on day 14 after bleomycin exposure." (PMID 35864207, 2022). "Compared with the control group, the BLM-induced pulmonary fibrosis group exhibited significantly higher expression of Fmod and Tgfbr2 mRNA; in contrast, the mRNA expression levels of Bambi, Skp1, Zfyve9, Zfyve16, Ppp2ca, Ppp2r1a, Ppp2r1b, Rps6kb1, and Rps6kb2 were markedly lower." (PMID 38259493, 2023). "Yao found that miR-7 can attenuate silica-induced pulmonary fibrosis by inhibiting TGFBR2, which plays an important role in EMT, but CDR1as can reverse miR-7-mediated repression of TGFBR2." (PMID 32765960, 2020). "In comparison to the neutrophilic cases, the IPA analysis of the proteomic datasets derived from horses with metachromatic inflammation revealed enrichment in pathways related to hypersensitivity reaction (CD44, ICAM1, SOD1, PSAP, CDH1) and lung fibrosis (AGER, TGFBR2, FBLN1, S100A9)." (PMID 39594673, 2024). "To explore the pathogenic significance of autocrine TGF-β signaling in fibrosis, we generated an AT2-specific Tgfbr2 conditional knockout mouse line, SftpcCreERT2; Tgfbr2flox/flox (hereafter Tgfbr2-cKO), to disturb TGF-β signaling in AT2-lineage cells and prepared a BLM-induced lung fibrosis model." (PMID 37653024, 2023). "We found that Acta2-reporter activity was comparable between BLM-treated and non-treated organoids of Tgfbr2-null AT2 cells, demonstrating that autocrine TGF-β signaling in AT2 cells plays a crucial role in fibroblast-to-myofibroblast differentiation in BLM-induced lung fibrosis." (PMID 37653024, 2023).
hepatocellular carcinoma (13 papers, 2012 to 2025). A malignant tumor that arises from hepatocytes. "It has been shown that TGF-β can induce the EMT and promote tumor cell invasion, whereas another study has shown that reduced TGFBR2 expression is associated with aggressive features of hepatocellular carcinoma." (PMID 22912877, 2012). "Tgfbr2 is a key molecule in TGFbeta signaling pathway and was found to prevent the formation of hepatocellular carcinomas and cholangiocarcinoma development." (PMID 29254483, 2017).
Sepsis (13 papers, 2021 to 2025). Sepsis is defined as life-threatening organ dysfunction caused by a dysregulated host response to infection. "USP11 inhibition by mitoxantrone ameliorated sepsis-associated AKI by downregulating TGFBR2/Smad3 signaling." (PMID 40656894, 2025). "We found that inhibiting USP11 ameliorated sepsis-associated AKI by regulating TGFBR2, suggesting that USP11 could be a potential therapeutic target for AKI." (PMID 40656894, 2025). "Herein, we hypothesize that inhibiting USP11 activity could regulate TGFBR2 in sepsis and provide protection against sepsis-associated AKI." (PMID 40656894, 2025). "Therefore, the underlying mechanisms of TGFBR2 in sepsis should be clearly elucidated." (PMID 33623823, 2021). "It would be both interesting and important to confirm upregulation of the TGFBR2/Smad signaling pathway in patients with sepsis." (PMID 40656894, 2025). "The present study reveals that USP11 is a key regulator of sepsis-induced AKI through modulation of the TGFBR2/Smad3 pathway." (PMID 40656894, 2025). "Alternatively, a decrease in miR-145 in lung epithelial cell-derived exosomes, which targets TGFBR2, leads to the inactivation of TGFBR2/Smad3 signalling, thus inhibiting lung injury induced by sepsis." (PMID 39104595, 2024). "further suggested that activation of the TGFBR2/Smad pathway was responsible for LPS-induced sepsis, resulting in increased levels of IL-2 and TNF-α and reduced overall survival of mice with sepsis." (PMID 35090386, 2022). "The level of miR-128-3p was decreased, and TGFBR2 expression was increased in serum samples of sepsis patients and LPS-induced HK2 cells." (PMID 33623823, 2021). "Results proved that the level of miR-128-3p was markedly downregulated, and the expression of TGFBR2 was notably upregulated in serum samples of patients with sepsis compared with control groups." (PMID 33623823, 2021). "In comparison with the healthy controls, CDKN2B-AS1 and TGFBR2 mRNA levels were significantly increased in serum samples from sepsis patients." (PMID 34126975, 2021). "TGFBR2 has attenuated the miR-145-mediated inhibition of sepsis progression in LPS-treated human umbilical vein endothelial cells." (PMID 34126975, 2021). "ELISA also indicated that the protein level of TGFBR2 was higher in 47 sepsis patients than that in 55 healthy controls." (PMID 34126975, 2021). "This study aimed to determine the regulatory network of miR-128-3p and TGFBR2 in lipopolysaccharide (LPS)-induced sepsis." (PMID 33623823, 2021). "To explore the roles of miR-128-3p and TGFBR2 in sepsis, we determined their levels by qPCR in serum samples from patients with sepsis." (PMID 33623823, 2021). "Subsequently, the expression levels of CDKN2B-AS1 and TGFBR2 in sepsis patients were determined by qRT-PCR." (PMID 34126975, 2021). "In this study, the levels of miR-128-3p and TGFBR2 in serum samples of sepsis patients and LPS-induced HK2 cells were detected." (PMID 33623823, 2021). "Pearson’s correlation coefficient analysis exhibited that CDKN2B-AS1 level was positively related to TGFBR2 level (P = 0.0013, r = 0.4547) in sepsis samples." (PMID 34126975, 2021). "In conclusion, we demonstrated that miR-128-3p was decreased and TGFBR2 expression was increased in serum samples of sepsis patients and LPS-induced HK2 cells." (PMID 33623823, 2021). "Overexpression of TGFBR2 abrogates miRNA-145-mediated inhibition of LPS-induced sepsis." (PMID 40656894, 2025). "The TGFBR2/Smad2 signaling pathway has a critical role in LPS-induced sepsis." (PMID 39057685, 2024). "TGFBR2 overexpression aggravates LPS-induced sepsis through up-regulating Smad2/3." (PMID 35264055, 2022). "Interestingly, online bioinformatics database showed that TGFBR2 had complementary binding sites for miR-128-3p, which prompted us to construct a miRNA-mRNA regulatory network in sepsis." (PMID 33623823, 2021). "CDKN2B-AS1 and TGFBR2 were abnormally upregulated in sepsis patients." (PMID 34126975, 2021).
Sepsis (continued). "Besides, upregulation of TGFBR2 abrogated miR-128-3p overexpression-mediated attenuation on LPS-induced sepsis, suggesting that miR-128-3p was involved in the development and progression of sepsis by regulation of TGFBR2." (PMID 33623823, 2021). "Our data showed that TGFBR2 was highly expressed in sepsis patients." (PMID 34126975, 2021). "In addition, the relationship between miR-128-3p and TGFBR2 was analyzed in serum samples of patients with sepsis." (PMID 33623823, 2021). "Knockdown of TGFBR2 promoted cell viability but reduced cell apoptosis and inflammation in LPS-treated BEAS-2B cells, indicating that TGFB2 might be associated with the sepsis-related lung injury." (PMID 34126975, 2021). "The TGF-β/Smad signaling pathway plays an important role in the progression of sepsis, and targeting the TGF-β receptor II (TGFBR2) has been shown to ameliorate its effects." (PMID 40656894, 2025). "CLP-induced sepsis upregulates USP11 and TGFBR2, leading to inflammation, oxidative stress, and renal damage." (PMID 40656894, 2025). "Elevated TGF-β and TGFBR2 levels have been detected in patients with sepsis, suggesting the critical role of TGF-β/Smad signaling in sepsis." (PMID 40656894, 2025). "We also detected enhanced expressions of TGFBR2 and phosphorylated Smad3, indicating increased activation of the TGF-β/Smad signaling pathway in sepsis." (PMID 40656894, 2025). "The work conducted by Cao showed that miR-145 inhibited LPS-induced inflammation and sepsis-induced lung injury via directly targeting TGF-β2 and inactivating TGFBR2/ Smad3 signaling both in septic patients and mice." (PMID 36012630, 2022). "miR-128-3p could inhibit apoptosis and inflammation by targeting TGFBR2 in LPS-induced HK2 cells, which might provide therapeutic strategy for the treatment of sepsis." (PMID 33623823, 2021). "Collectively, miR-128-3p could inhibit apoptosis and inflammation by targeting TGFBR2 in LPS-induced HK2 cells, providing viable therapeutic avenues for the treatment of sepsis." (PMID 33623823, 2021).